IGFL4 (IGF like family member 4)
Tractability: Antibody: UniProt places it where antibodies can reach, with high confidence; UniProt predicts a signal peptide or a membrane-spanning region; its Gene Ontology location is reachable by antibodies, with medium confidence.
Gene: Protein-coding gene on chromosome 19 (46,039,182 to 46,077,118, reverse strand). Ensembl gene ENSG00000204869.
Subcellular location: Secreted
Subcellular location (Human Protein Atlas): Cytosol; Predicted to be secreted
Gene Ontology:
Molecular function: signaling receptor binding
Cellular component: extracellular region
Genetic constraint (gnomAD): Loss-of-function variants: 11 observed, 14.51 expected, observed/expected ratio (o/e) 0.76, 90% interval 0.48 to 1.25. The upper end of that interval is the gene's LOEUF score, 1.25, which puts it in group 5 of 6, group 1 being the genes least tolerant of losing a copy. Missense variants: 110 observed, 136.05 expected, observed/expected ratio (o/e) 0.81, 90% interval 0.69 to 0.95. Synonymous variants: 46 observed, 51.37 expected, observed/expected ratio (o/e) 0.9, 90% interval 0.71 to 1.14.
Homologues: Orthologues: chimpanzee IGFL4 (96% identical), macaque IGFL4 (81% identical), rat AC093995.2 (34% identical), mouse Igfl3 (31% identical). Paralogues in human: IGFL3 (44% identical), IGFL2 (40% identical), IGFL1 (28% identical).